RNU7-30P (RNA, U7 small nuclear 30 pseudogene)
Synonyms: U7.30
Gene: Small nuclear RNA gene on chromosome 14 (91,091,077 to 91,091,138, forward strand). Ensembl gene ENSG00000252644.
Homologues: Orthologues: chimpanzee U7 (98% identical), macaque U7 (95% identical), pig U7 (77% identical). Paralogues in human: RNU7-1 (85% identical), RNU7-125P (85% identical), RNU7-14P (85% identical), RNU7-2P (85% identical), RNU7-52P (85% identical), RNU7-56P (85% identical), U7 (85% identical), RNU7-11P (84% identical), RNU7-13P (84% identical), RNU7-4P (84% identical), RNU7-55P (84% identical), RNU7-60P (84% identical), and 143 more.